MIR6730 (microRNA 6730)
Synonyms: hsa-mir-6730
Gene: MicroRNA gene on chromosome 1 (12,578,957 to 12,579,023, reverse strand). Ensembl gene ENSG00000276830.
Diseases named in the same sentence as MIR6730 in open-access papers:
MIR6730 is named in the same sentence as 2 diseases in open-access papers, as found by Europe PMC text mining. Sharing a sentence is not in itself a finding about the gene and the disease.
MIR6730 shares sentences with these, for which no sentence is quoted: lung carcinoma (1 paper); tumor (1).